TRPM2 (transient receptor potential cation channel subfamily M member 2)
Diseases named in the same sentence as TRPM2 in open-access papers (continued):
Sharing a sentence is not in itself a finding about the gene and the disease.
tumor (continued). "Tumor growth of cells with TRPM2 deletion was restored to that of control cells by TRPM2 reconstitution, demonstrating absence of significant secondary off-target effects in KO cells." (PMID 35428820, 2022). "In this study, for the first time, we analyzed the correlation between TRPM2 expression and its prognostic value in various cancers and the tumor immune cell infiltration in KIRC." (PMID 35071322, 2021). "Subsequently, the Tumor Immune Estimation Resource (TIMER) platform and the TISIDB website were used to assess the correlation between TRPM2 and tumor immune cell infiltration level." (PMID 35071322, 2021). "In both GC patient tumours and cultured cell lines, gain of promoter activity in the TRPM2 gene leads to the expression of a cancer-specific isoform." (PMID 33499898, 2021). "Immunostaining images for different stage groups showed TRPM2 expression in protein level was statistically significantly increasing as the tumor stage increased and tumor specimens had higher level than para-tumor specimens (P < 0.05)." (PMID 34099637, 2021). "Then, the TISIDB database was used to further explore the correlations between the level of TRPM2 and the 28 tumor immune-infiltrating cell subtypes." (PMID 35071322, 2021). "TRPM2 (transient receptor potential melastatin-2), a Ca2+ permeable, non-selective cation channel, is highly expressed in cancers and regulates tumor cell migration, invasion, and proliferation." (PMID 35071322, 2021). "We found that TRPM2 was the only molecule of TRPM family that highly expressed in tumor than para-tumor specimens in the RNA level (P < 0.05)." (PMID 34099637, 2021). "We assessed the correlation between the expression of TRPM2 and the level of tumor-infiltrating immune cell gene markers in KIRC and BLCA using the TIMER database." (PMID 35071322, 2021). "Among these cancer types, the expression level of TRPM2 was most relevant with the tumor subtype, stage, grade, and lymph node metastasis in KIRC." (PMID 35071322, 2021). "Subsequently, it was demonstrated that expression of TRPM2 (transient receptor potential cation channel, subfamily M2) on tumor cells increased their sensitivity to neutrophil-mediated, H2O2-dependent, cytotoxicity." (PMID 32849639, 2020). "Recent research in mouse BC models revealed that ROS-mediated cell lysis was dependent on Ca2+ channels and mediated by transient receptor potential cation channel, subfamily M, member 2 (TRPM2) expression on tumor cells." (PMID 32849640, 2020). "ROS-mediated cell killing wasshown to be dependent on tumor cell expression of TRPM2, an H2O2-dependent calciumchannel, which upon activation results in a lethal influx of calcium ions into thecell." (PMID 32425992, 2020). "TRPM2 upregulation in tumor cells occurred following an epithelial-to-mesenchymal transition (EMT) and cancer cells that have undergone an EMT were more susceptible to neutrophil-mediated killing." (PMID 32849639, 2020). "In collaboration with G–CSF, tumor cell-derived CCL2 educated neutrophils to migrate into pre-metastatic lung and to produce HOCl, thereby inhibiting breast cancer seeding to lungs, probably by acting on TRPM2 expressed in tumor cells." (PMID 32422991, 2020). "In different cancer cells, an increase in [Ca2+]i through activation of TRPM2 channels increased the rate of cell migration, presumably tumor invasion." (PMID 30984336, 2019). "A former in vivo investigation evidenced 8-Br-ADPR as the sole secondary messenger to antagonise TRPM2 by blocking sustained tumour-induced Ca2+ signals and degranulation by western blot and confocal microscopy." (PMID 31796045, 2019). "We showed that TRPM2 is expressed in the GCT-derived tumor cell line KGN and calcium imaging suggested its functionality." (PMID 31671815, 2019). "Our studies suggest that a systemic inhibition of TRPM2 would be required to alleviate the effects of radiation on skin damage." (PMID 30483886, 2019).
tumor (continued). "Of note, higher expression of IQGAP, as seen in TRPM2 expressing cells, has also been reported to contribute to tumor proliferation, invasion, and angiogenesis." (PMID 31575956, 2019). "It has been recently revealed that the H2O2 secreted by neutrophils leads to tumor cell death, and TRPM2-mediated calcium influx acts as a go-between for this tumor killing process by neutrophils in AT3 and 4T1 breast cancer." (PMID 31474975, 2019). "The current results are the first to compare the effect of CURC on CISP-induced TRPM2 channel activation and cell death through excessive ROS production in Hep2 tumor cells." (PMID 31780732, 2019). "A recent in vivo mouse investigation discovered a novel anti-tumour mechanism in NK cells via a ADPR-CD38 synergy with TRPM2." (PMID 31796045, 2019). "Here, to examine the link between Ca2+ influx through TRPM2 and preservation of tumor viability and mitochondrial function, the Ca2+-dependent kinase Pyk2 and downstream signaling pathways were studied." (PMID 30020827, 2018). "To evaluate the possibility that TRPM2-mediated Ca2+ signaling is required for the antitumor effector function of NK cells, we first examined the tumor-induced Ca2+ change in NK cells from TRPM2+/+ and TRPM2−/− mice." (PMID 25879940, 2015). "Consistent with our finding that TRPM2−/− NK cells have decreased cytolytic activity, we observed a defect in the ability of TRPM2 deficient mice to control B16F10 tumor formation and their consequent survival rates." (PMID 25879940, 2015). "Following B16F10 tumor cell injection, a markedly higher number of metastatic cells were observed in TRPM2−/− NK cell-treated mice than in TRPM2+/+ NK cell-treated mice." (PMID 25879940, 2015). "Similar to the findings observed with CD38 and TRPM2 in NK cells, perforin was scattered inside the NK cells mostly inside cytolytic granules and co-localizing with TRPM2 even before stimulation with tumor cells." (PMID 25879940, 2015). "Collectively, these findings demonstrate that ZGE modulates multiple stress‐responsive pathways in tumor tissues, attenuating oxidative damage (via TRPM2 and SOD2), amplifying inflammatory signaling (via TNF‐α), and promoting apoptosis (via caspase‐3), particularly when combined with DOX treatment." (PMID 41306344, 2025). "This suggests that TRPM2 may promote tumor progression by fostering an immunosuppressive microenvironment through M2 macrophage polarization, making it a potential target for immunotherapy in OC." (PMID 40330466, 2025). "This dependence underscores the interplay between ROS and TRPM2 in facilitating tumor cell death." (PMID 40282474, 2025). "TRPM2 expression is positively correlated with M2 macrophages, which are tumor-promoting and linked to immunosuppression, rather than M1 macrophages, which have tumor-suppressing functions." (PMID 40330466, 2025). "While TRPM2 activation may confer survival advantages to tumor cells, its overactivation in non‐cancerous tissues contributes to cytotoxicity and inflammation." (PMID 41306344, 2025). "High TRPM2 expression in various cancers suggests that TRPM2 promotes tumor cell survival." (PMID 39007141, 2024). "Furthermore, Western blot results also indicated that the supernatant of tumor cells treated with NP4 promoted TRPM2 protein expression in macrophages." (PMID 39477929, 2024). "TRPM2, known to be H2O2‐dependent and frequently upregulated in cancer renders tumor cells more vulnerable to neutrophil‐mediated killing, and cells expressing reduced levels of TRPM2 were protected from neutrophil cytotoxicity and exhibited enhanced seeding in the pre‐metastatic lung." (PMID 38062888, 2023). "The results closely followed those from previous analyses: TRPM2 expression was significantly different in different immune and molecular subtypes in most cancers, which reflected the biomarker potential of TRPM2 in subtyping and guiding tumor therapeutic strategies." (PMID 37569287, 2023).
tumor (continued). "The TRPM2 protein has also been proven to maintain the viability of tumor cells in various cancers." (PMID 37762313, 2023). "TRPM2 inhibition or depletion reduces cell and mitochondria Ca2+ influx and decreases activity, autophagy, antioxidant response, and mitochondrial function, thus impairing tumor cell survival." (PMID 37892239, 2023). "Recent studies have shown that TRPM2 inhibition decreases glutamine production, thus decreasing antioxidant cofactors and the antioxidant response, increasing cancer cell death and reducing tumor growth." (PMID 37337283, 2023). "TRPM2 also has immunomodulatory functions and can influence the tumor microenvironment." (PMID 37892239, 2023). "TRPM2 activation in immune cells, such as macrophages and dendritic cells, affects their polarization and cytokine production, leading to a modulation of the anti-tumor immune response." (PMID 37892239, 2023). "Various neutrophil-mediated tumor cell-killing mechanisms have been described, including direct contact and the generation of ROS, NO production, and the induction of calcium influx into tumor cells via the TRPM2 channel." (PMID 36768342, 2023). "Additionally, TRPM2-mediated Ca2+ influx influences the release of inflammatory mediators that promote tumor growth and angiogenesis." (PMID 37892239, 2023). "Additionally, although the expression of TRPM2 has been detected in many immune cell types, the function of TRPM2 in anti-tumor immunity has remained elusive." (PMID 37569287, 2023). "Several studies report that TRPM2 pharmacological inhibition could lead to a decreased tumor proliferation and viability, enhancing cell death and increasing drug sensitivity." (PMID 37081976, 2023). "The results indicated that TRPM2 expression could easily distinguish tumor tissues from normal renal tissues with the area under the curve (AUC) of 0.9651 (95% CI: 0.9447-0.9854; P<0.0001)." (PMID 36619219, 2023). "As expected, TRPM2 was highly expressed in macrophages and malignant cells in the tumor microenvironment, suggesting that TRPM2 may play a role in communication between immune cells and cancer cells." (PMID 37569287, 2023). "The differential expression of TRPM2 between tumors and corresponding normal tissues suggested that TRPM2 may be helpful in distinguishing tumor patients from healthy individuals." (PMID 37569287, 2023). "In vitro experiments showed TRPM2 enhanced malignant potential of tumor cells." (PMID 36619219, 2023). "Upregulation of TRPM2 channels could stimulate pancreatic cancer processes (proliferation, migration, and invasion), independently of the tumor cell type (PANC-1, BxPC-3), and of the tumor-bearing mice model." (PMID 36844925, 2022). "TRPM2 accelerated tumor cell proliferation and maintain their survival via multifarious regulation mechanisms, including activating JNK-signaling, motivating PKC/MAPK pathways, and enhancing mitochondrial function by promoting mitophagy and suppressing reactive oxygen species (ROS) levels." (PMID 36008839, 2022). "Compared to normal breast cells, TRPM2 inhibition in tumor breast cells produces a significant increase in damaged DNA levels, hypothesizing that TRPM2 activity in the nucleus could facilitate the integrity of genomic DNA, by promoting nuclear calcium influx." (PMID 36844925, 2022). "Therefore, besides initiating an apoptotic cascade in the tumor, TRPM2 supports neutrophil recruitment to tumor sites." (PMID 36514901, 2022). "Consequently, TRPM2 has 2 distinct anti-tumor functions: promoting neutrophil recruitment to tumor sites and activating the apoptotic cascade in the tumor cells themselves." (PMID 36514901, 2022). "TRPM2 is markedly expressed in prostate cancer cells (PCa) compared to the normal prostate epithelium, and its expression fuels in parallel with increasing clinical tumor grade." (PMID 36844925, 2022). "We also verified that the changes of KEAP1 and NRF2 were corresponded with TRPM2 KO in tumor cells." (PMID 34226519, 2021).
tumor (continued). "Furthermore, we used the TIMER and TISIDB databases to assess the correlation between TRPM2 and the abundance of tumor-infiltrating immune cells in the TME." (PMID 35071322, 2021). "When further knocking out TRPM2 in A549 tumor cells, similar results were also observed." (PMID 34226519, 2021). "Interestingly, TRPM2 expression was higher in disseminated circulating 4T1 tumor cells compared to the primary tumor, and its expression profile was associated with a more pronounced mesenchymal phenotype." (PMID 34360952, 2021). "TRPM2 is involved in the regulation of tumor immune infiltration in KIRC." (PMID 35071322, 2021). "Moreover, neutrophil-derived superoxide induced calcium influx in tumor cells by acting on transient receptor potential cation channel, subfamily M, member 2 (TRPM2), expressed in cancer cells and eventually cell lysis." (PMID 32422991, 2020). "Therefore, CISP applications are characterized in the Hep2 cell by increases in TRPM2 channel and caspase activation through excessive ROS production, but also decreases in tumor cell viability, RGS and GSPx." (PMID 31780732, 2019). "In addition, tumor cells must be susceptible to neutrophil cytotoxicity (i.e., express the H2O2-dependent TRPM2 Ca2+ channel) for neutrophils to exert this favorable function." (PMID 31379884, 2019). "Due to the importance of enhanced ROS and ROS-activated TRPM2 channel activation on tumor cell death, we have investigated the effect of CURC on CISP-induced TRPM2 current density, TRPM2 expression level and Ca2+ fluorescence intensity values through oxidative stress stimulation in the Hep2 cells." (PMID 31780732, 2019). "Immunohistochemistry showed parallel expression of NOX4 and TRPM2 in all 73 tumor samples examined." (PMID 31671815, 2019). "Hence, TRPM2 channels serve as targets of therapeutic agents to limit tumor growth and tumor-induced Ca2+ entry in cancer treatments." (PMID 30984336, 2019). "Since TRPM2 expression in tumor cells varies, not all tumor cells are equally susceptible to neutrophil cytotoxicity." (PMID 31379884, 2019). "Due to the significance of enhanced ROS and ROS-activated Ca2+ entry (through TRPM2 channel activation) for tumor cell apoptosis, the pro-oxidant action of CURC may enhance CISP efficacy for cancer management." (PMID 31780732, 2019). "Moreover, intracellular production of ADPR by CD38 was reported in NK cells and shown to modulate Ca2+ signalling by gating TRPM2 channels and contributing to the anti-tumor activity of NK cells." (PMID 29463868, 2018). "We further evaluated the ability of TRPM2 to protect against B16F10 tumor growth in vivo." (PMID 25879940, 2015). "Thus, CD38 and TRPM2 cooperate to generate the sustained Ca2+ signal and directed migration of cytolytic granules to the immunological synapse in response to tumor stimulation." (PMID 25879940, 2015). "Finally, our results unveiled the critical role of TRPM2 in NK cell cytotoxicity against tumor cells when NK cells were introduced to mice bearing B16F10 cells as passive immunotherapy." (PMID 25879940, 2015). "Thus, we further explored whether blocking or enhancing TRPM2 activity influenced the anti-tumor effect of cisplatin." (PMID 37649595, 2023). "The results indicated that TRPM2 exhibited significantly higher expression in the immune-infiltrated phenotype than in the immune-deserted phenotype, suggesting that TRPM2 is potentially involved in the immune response of tumor tissues and may be a promising target for future immunotherapy." (PMID 37762313, 2023). "This indicates that, among these cancer types, tumor cells with high TRPM2 expression may have a stronger capacity for self-renewal and proliferation compared to those with low TRPM2 expression, and TRPM2 may promote tumor aggressiveness by enhancing the stemness of tumors cell." (PMID 37569287, 2023). "Thus, we speculated that TRPM2 might be involved in the process of promoting tumor progression mediated by M2 macrophages." (PMID 37608401, 2023).
tumor (continued). "Moreover, the strong positive correlations across the immune checkpoint genes indicated that TRPM2 may be able to form positive feedback with certain immune checkpoint genes, facilitating the immune escape of tumor cells." (PMID 37569287, 2023). "In the present study, we first explored TRPM2 expression features among pan-cancer and discovered that TRPM2 tended to be highly expressed in almost all TCGA cancers, which indicated that TRPM2 could function as an oncogene for tumor growth and progression." (PMID 37569287, 2023). "However, the Pearson coefficient between TRPM2 and tumor stage was 0.81." (PMID 34099637, 2021). "According to research findings, when TRPM2-mediated calcium influx is inhibited, the mitochondria are dysfunctional, cellular bioenergetics is reduced, and the production of ROS is increased, thereby decreasing tumor growth and increasing chemotherapy sensitivity." (PMID 35071322, 2021). "Importantly, the increased TRPM2 expression that is associated with EMT in circulating tumor cells renders them more susceptible to neutrophil cytotoxicity, as neutrophil-secreted H2O2 will activate TRPM2 via ADP-ribose formation and result in calcium-overload associated apoptosis." (PMID 34360952, 2021). "Thus, we speculated that CD38-cADPR signal at least in partly through the activation of TRPM2 to promote the tumor survival." (PMID 34226519, 2021). "However, no study has yet demonstrated the association of TRPM2 with the prognosis of cancer patients or tumor immune infiltration, and the possibility and the clinical basis of TRPM2 as a prognostic marker in cancers are yet unknown." (PMID 35071322, 2021). "The cited studies also confirm our analyses in which we showed that in tumor cells TRPM2 gene expression is significantly decreased whereas PARP1 and PARP2 expression is significantly increased, which may indicate that TRPM2 gene loses its function in tumor cells." (PMID 32423430, 2020). "The finding that perforin migration towards the synapse requires CD38 as well suggests that both CD38 and TRPM2 are absolutely essential for the migration of perforin (or possibly cytolytic granules as well) toward the immunological synapse when NK cells encounter tumor cells." (PMID 25879940, 2015). "Specifically, TRPM1 and TRPM2 were upregulated in tumor tissues, whereas TRPM4, TRPM6, TRPM7, and TRPM8 were downregulated in the tumor group." (PMID 41562086, 2025). "In the following subsections, we will examine the role of TRPML1, TRPA1, TRPM2 and TRPV1 in cancer processes mediated by oxidative stress in different tumor types." (PMID 40813985, 2025). "TRPM2 is activated by H2O2 secreted by neutrophils and mediates apoptosis by inducing Ca2+ influx in tumor cells." (PMID 39633507, 2024). "In our study, the differential expression of TRPM2 and TRPM4 in tumor and para-carcinoma tissues was extremely clear, indicating the important role of these TRP family genes in the tumorigenicity in various cancers." (PMID 36830651, 2023). "The result from the Cancer Cell Line Encyclopedia (CCLE) database also suggested that the expression level of TRPM2 was relatively high in LAML, PRAD, ALL, UCEC, ESCA, LCML, COAD/READ, OV, and BRCA tumor cells." (PMID 37569287, 2023). "Therefore, despite the pro-proliferative role of TRPM2 in several cancer cell lines, inhibition of its activity by tumour extracellular acidic pH might result in cancer cells’ protection from neutrophil cytotoxicity, with overall major efficiency in dissemination." (PMID 35806388, 2022). "TRPM2 channel silencing considerably reduced the expression of EMT markers (N- and E-cadherin, twist, and snail), while increasing tumor suppressor PTEN activities." (PMID 36844925, 2022). "TRPM2 expression is increased in tumor cells undergoing epithelial-to-mesenchymal transition, thus leading to increased production of CXCL2 by tumor cells and neutrophil recruitment to tumor sites." (PMID 36514901, 2022).